FOS (Fos proto-oncogene, AP-1 transcription factor subunit)
Diseases named in the same sentence as FOS in open-access papers (continued):
Sharing a sentence is not in itself a finding about the gene and the disease.
Obesity (26 papers, 2014 to 2025). Accumulation of substantial excess body fat. "Increased expression of PDK1 and PDK2 by JUN and FOS enforces HIF1a stability to facilitate adipocyte differentiation and obesity." (PMID 34552205, 2021). "Further analysis of human tumor tissues, incorporating clinical data, revealed that patients with relatively high FOS hepatic expression also had higher body weight (n = 344) or higher body mass index (BMI) (n = 335, 158/335 BMI > 25 kg m−2), consistent with increased FOS in obesity." (PMID 41024433, 2025). "The NF-κB target genes IRF1, STAT1, JUN, HSP90AA1, FOS, and EGR1, were enriched in the pathway of Glucocorticoid receptor regulatory network and homeostasis pointing towards their critical role in obesity." (PMID 31013288, 2019). "Lastly, our results suggest an obesity‐related regulatory switch involving two transcription factors, MYC and FOS, which may drive the distinctive endotypes we observe." (PMID 37006170, 2023). "The FOS had no changes in the distribution between phases 1 and 4, 54.54% in normal weight, 27.27% in overweight, and 18.19% in severe obesity." (PMID 35910449, 2022). "The NF-κB target genes JUN, PIK3R1, FOS, and IGF1R are enriched in the insulin signaling pathway which could contribute to obesity related disorders." (PMID 31013288, 2019). "Moreover, STAT3, MCL1, PMAIP1, SOD2, FOXO3, FOS, FKBP5 may play an essential role in the genesis and growth of obesity and might serve as a possible therapeutic target." (PMID 34712134, 2021). "Interestingly, all tissues of T2D patients showed altered expression of genes involved in the inflammation response—such as SOCS1 in WB; CCL20 and SLAMF1 in SAT; ACP5, FOS, and JUN in VAT; and PLA2G2A in LT, showing the relevance of the systemic chronic inflammation in obesity and T2D." (PMID 29466957, 2018).
ovarian carcinoma (26 papers, 2008 to 2025). A malignant neoplasm originating from the surface ovarian epithelium. "A well-differentiated phenotype, more metastases than primary tumors, and an independent positive prognostic sign are all associated with high c-FOS expression in ovarian cancer (OvCa)." (PMID 41233892, 2025). "However, in some tumours, such as ovarian cancer, high c-FOS is associated with tumour suppressor activity and improved prognosis." (PMID 40438247, 2025). "However, in some cases the expression of FOS has been related to apoptosis, and its loss in human gastric and ovarian carcinomas was associated with disease progression." (PMID 31590218, 2019). "Contrarily, c-FOS, a negative regulator of E-selectin, significantly reduced ovarian cancer growth both in vitro and in vivo." (PMID 35464064, 2022). "For instance, it was shown that overexpressing c-FOS ovarian cancer cells had lower selectin ligands sLea and sLex and diminished adhesion to E-selectin, thereby reducing metastasis in an intraperitoneal xenograft mouse model." (PMID 35464064, 2022). "Moreover, FOS involvement in the development of multidrug resistance in some tumors, such as breast and ovarian cancer." (PMID 36609277, 2023). "In conclusion, we suggest that KRAS, NOXA, PUMA, c-FOS, and c-JUN may be associated with poor prognosis in ovarian cancer." (PMID 35807169, 2022). "It was also observed that c‐FOS might influence ovarian cancer progression through its pro‐apoptotic effect and by altering peritoneal adhesion of OC cells." (PMID 34346538, 2021). "Evidences for c-FOS overexpression as promoting apoptosis and delaying ovarian cancer progression in preclinical models may be supported by the findings in these clinical specimens." (PMID 33256002, 2020). "An increase in the expression level of mRNA and protein in women with ovarian cancer was observed for KRAS, c-FOS, and EGFR." (PMID 35807169, 2022). "An increase in the expression level of mRNA and protein in women with ovarian cancer was observed for KRAS, c-FOS, PUMA, and EGFR." (PMID 35807169, 2022). "In summary, we provided evidence that KRAS, NOXA, PUMA, c-FOS, and c-JUN could be promising biomarkers in ovarian cancer." (PMID 35807169, 2022). "Notably, two MEK inhibitors (PD0325901 and Trametinib) were effective in eliminating ovarian cancer cells in combination with JQ1, consistent with our observation that JQ1 treatment activated MAPK targets EGR1 and FOS." (PMID 26575423, 2016).
glioma (23 papers, 2010 to 2025). A benign or malignant brain and spinal cord tumor that arises from glial cells (astrocytes, oligodendrocytes, ependymal cells). "The FOS promoter caused significantly higher transcriptional activity in glioma cell lines than all alternative promoters with the exception of CMV." (PMID 26571389, 2015). "Targeting FOS in the FOS/GABP/mutant TERT cascade might be an effective therapeutic strategy for gliomas harboring TERT promoter mutations." (PMID 37372381, 2023). "Therefore, we focused on tumor-associated genes and hypothesized that the FOS promoter may be a potential tool for glioma gene therapy." (PMID 26571389, 2015). "mRNA analysis shows increased FOS levels in high grade glioma tissue compared with low grade glioma and normal brain tissue." (PMID 26571389, 2015). "Adenoviral-mediated delivery of the HSV-tk gene controlled by the FOS promoter conferred a cytotoxic effect on human glioma cells in vitro and in vivo." (PMID 26571389, 2015). "This study suggests that use of the FOS-tk adenovirus system is a promising strategy for glioma-specific gene therapy but still much left for improvement." (PMID 26571389, 2015). "Compared with TERT, Survivin, Cox2 and E2F1 promoter, the transcriptional activity of FOS promoter was higher in glioma cell lines." (PMID 26571389, 2015). "The data presented indicate that the use of FOS-TK adenovirus system is a promising strategy to deliver glioma-specific gene therapy but still much left for improvement." (PMID 26571389, 2015). "We found that adenoviral-mediated delivery of the HSV-tk gene controlled by the FOS promoter can confer cytotoxic effect on human glioma cells in vitro and in vivo." (PMID 26571389, 2015). "In view of our finding that the FOS expression vector can selectively express target genes in glioma cells, we engineered a therapeutic cfos-TK adenovirus system that drives expression of HSV-tk and GFP (Ad-FOS-HSVtk-IRES- GFP)." (PMID 26571389, 2015). "Compared with the TERT, Survivin, Cox2 and E2F1 promoters, the transcriptional activity of the FOS promoter was higher in all three glioma cell lines.." (PMID 26571389, 2015). "In conclusion, we have developed a glioma-specific gene therapy system that expresses the HSV-tk suicide gene under direct transcriptional control of the FOS promoter, and have validated the therapeutic effects of this system in glioma in vitro and in vivo." (PMID 26571389, 2015). "In the three glioma cells lines, we compared the rate of inhibition of cell growth of Ad-FOS-HSVtk-IRES-GFP to that of Ad-CMV-HSVtk-IRES-GFP." (PMID 26571389, 2015). "The bioinformatics analysis showed that miR-603 and miR-4791 may down-regulate FOS, and miR-603 can promote the growth of glioma cells via the Wnt/β-catenin pathway." (PMID 33393628, 2021). "However, the transcriptional activity and expression selectivity of the FOS promoter in human glioma cell lines remains untested." (PMID 26571389, 2015). "On the basis of these results, we decided to determine whether the Ad-FOS-HSVtk adenovirus system affects the growth of glioma in vivo." (PMID 26571389, 2015). "Similar pattern was observed in the expression level of FOS in the malignant glia clusters 0, 2 and CCL4L2 between the subcluster 0, 3, suggesting these genes might be vitally implicated in the progression of certain type of glioma malignant cells." (PMID 39033204, 2024). "Therefore, by expressing HSVtk under the FOS promoter, we demonstrated selective inhibition of cancer cells, a crucial requirement for the establishment of Ad-FOS-HSVtk as a potential therapeutic agent for glioma." (PMID 26571389, 2015). "Data from GEPIA2 also showed frequently increased FOS, JUNB, JUN, and ATF3 in glioma, especially GBM samples, compared to normal brain tissues." (PMID 39257581, 2024). "A strategy to limit BV-mediated transgene expression to tumor cells is the use of glioma-specific promoters such as SSX4 and FOS." (PMID 36992317, 2023).
glioma (continued). "Transcription factor PAX5 (Paired Box Gene 5) promotes gliomagenesis and cooperates with factors such as MYC, FOS, or JUN, which are highly expressed in gliomas." (PMID 36850002, 2023). "In this study, we compared the transcriptional activities of FOS, TERT, Survivin, E2F1, Cox2 and CMV promoter in human glioma lines." (PMID 26571389, 2015). "The FOS promoter showed 13.9%, 32.4%, and 70.8% of the transcriptional activity of CMV in three glioma cell lines (U87, U251, and U373)." (PMID 26571389, 2015). "In addition, we evaluated the correlation between the expression of the top 3 hub genes, STAT3, FOS and TLR4, in the grade 4 glioma tissue and model 1 miRNAs, miR-362-3p and miR-6721-5p, in serum." (PMID 38455766, 2024). "By contrast, XIII-WT and XVII-WT cells were enriched for a number of FOS::JUN family transcription factors motifs, which have previously been identified to either be enriched in wild-type H3K27 high-grade gliomas or shared across multiple glioma subtypes." (PMID 35590427, 2022). "We compared the activity of the FOS (FBJ murine osteosarcoma viral oncogene homolog) promoter with five alternative tumor-specific promoters in glioma cells and non-malignant astrocytes." (PMID 26571389, 2015).
bladder cancer (22 papers, 2015 to 2026). "From the perspective of the direct targeting of molecules, it has been demonstrated that the inhibition KPNA2 (e.g., via the PRDM1/c-FOS pathway) has antitumor effects in bladder cancer models." (PMID 41413918, 2025). "Overexpression of miR-490-5p in T24 bladder cancer cells significantly reduced the expression of c-FOS, inhibiting cell proliferation and invasion, and inducing cell apoptosis." (PMID 33149754, 2020). "Meanwhile, FOS is reported as an oncogene in several kinds of cancers such as bladder cancer and HCC." (PMID 28302149, 2017). "Overexpression of miR-101 inhibits the proliferation and invasion of bladder cancer cell line T24, potentially through the regulation of c-FOS expression." (PMID 28947955, 2017). "However, one previously verified target gene, FBJ murine osteosarcoma viral oncogene homolog (c-FOS), is implicated in cellular proliferation in human bladder cancer." (PMID 41468376, 2025). "Binding sites for the FOS and JUN components of AP1 are present in the AXL promoter and functional studies have confirmed their involvement in the regulation of AXL expression in chronic myeloid leukemia (CML) and bladder cancer, respectively." (PMID 28251492, 2017).
pancreatic cancer (21 papers, 2011 to 2025). "FOS, which encodes leucine zipper protein, was reported to be over-expressed in pancreatic cancer and was closely correlated with tumor proliferation, differentiation, and apoptosis." (PMID 34290570, 2021). "The discovery of FOS in both methods thus highlights its importance for tumor progression and outcome in pancreatic cancer, and further underlines the ability of our method to find reproducible and biologically significant markers." (PMID 22615549, 2012). "In pancreatic cancer cells, MSI-2 loss led to down-regulation of many key proto-oncogenes including c-FOS." (PMID 29073938, 2017). "For example, deletion of LATS1/2 in organoids or in a mouse model of pancreatic cancer led to the activation of AP-1 and YAP target genes, where YAP physically interacts with the FOS/JUN complex." (PMID 35883668, 2022). "In addition, this study demonstrated the role of abnormal pathways such as Wnt and Notch in pancreatic cancer and identified new genes such as EGLN3, MMP9, and FOS KLF5 and other transcription factors involved in carcinogenesis." (PMID 36052088, 2022).
colitis (19 papers, 2013 to 2025). Inflammation of the colon. "In a colitis model in rats, inulin, and FOS reduced colitis, which was associated with increased Bifidobacterium species and reduced Enterobacteriaceae and C. difficile in the feces." (PMID 24600450, 2014). "H3K9me2 regulates IL-17 in a murine T cell transfer model of colitis, IL-6 in an inflammatory vascular smooth muscle cell model, Il-8 in an inflammatory intestinal epithelial cell model, and c-FOS in an aged-related impaired memory neuronal cell model." (PMID 39768289, 2024). "In addition, administration of oral inulin reduced the severity of dextran sodium sulphate (DSS)-induced colitis in rats and increased proportions of Lactobacillus and Bifidobacterium in spontaneous colitis-developed transgenic rats treated with oligo-fructose enriched inulin (OF-IN) or FOS." (PMID 31430948, 2019).
endometriosis (19 papers, 2012 to 2025). The growth of functional endometrial tissue in anatomic sites outside the uterine body. "This series of research findings encompass multiple crucial roles of c-FOS in developing endometriosis, spanning from gene expression to protein activity." (PMID 38098472, 2023). "In an open, prospective, and controlled study, it was found that the expression levels of the c-FOS gene were higher in patients with endometriosis compared to normal endometrium." (PMID 38098472, 2023). "High expression of FOS has already been reported in the eutopic endometrium of women with endometriosis." (PMID 31941945, 2020). "Additionally, immune histochemical results revealed a more abundant distribution of c-FOS protein in the extracellular matrix of endometriosis tissues." (PMID 38098472, 2023). "The altered expression and distribution of FOS protein prompted endometriosis in the baboon." (PMID 35799127, 2022). "Repeated genes from the MS-phase (CCN1, CRISP3, EGR1, FOS, FOSB, and TRPM6) could be associated with affected receptivity in endometriosis." (PMID 32474803, 2020). "Furthermore, we find that FOS is comparatively more upregulated in the moderate-to-severe disease stage, and that its upregulation is only minimally impacted by the use of hormonal therapy for both peritoneal lesions and deep infiltrating endometriosis." (PMID 40747097, 2025). "FOS is an early transcription factor that has been reported to be related to estradiol-dependent cell proliferation and may play a role in the molecular mechanisms of estrogen action on the induction, promotion, or progression of endometriosis." (PMID 22952593, 2012). "Here, the genes FOS and DES were particularly highly upregulated in endometriosis patients compared to controls." (PMID 41516028, 2025). "The significant upregulation of genes such as FOS and DES in endometriosis patients, compared to controls, suggests dysregulated cellular processes critical for tissue organization, motility, and even hematopoietic functions." (PMID 41516028, 2025). "In endometriosis, JUNB collaborates with AP-1 members (e.g., FOS, FOSB) to drive early-stage M1 polarization and inflammation, mirroring our findings in denervated muscle." (PMID 40917776, 2025). "Five estrogen-responsive genes, CYP19A1, EGFR, ESR2, FOS, and IGF1, were found to be modified in human endometriosis, uterine tumor and breast tumor tissues." (PMID 36401252, 2022). "In women with endometriosis, upregulation of JUNB mRNA, FOS mRNA and FOS protein in secretory endometrium was reported." (PMID 32933042, 2020).
diabetes (18 papers, 2014 to 2025). "The regulation of BM-MSCs of patients with type 2 diabetes mellitus (T2DM) by SCD-1 is a necessary condition for osteogenesis mediated through the miR-203a/FOS and miR-1908/EXO1 regulatory pathways." (PMID 33319811, 2020). "For example, in the TF–miRNA regulatory network of diabetes mellitus, we found all of the TFs (FOS, PPARG, HNF1B) with high degree centralities were validated to be associated with diabetes mellitus in related publications." (PMID 30371815, 2019). "The present study revealed that SCD1 is involved in the regulation of hsa-miR-203a and hsa-miR-1908, which mediate the expression of FOS and EXO1 and may be associated with diabetic fracture." (PMID 32454462, 2020). "In summary, the newly proposed SCD1/miR-203a/FOS and SCD1/miR-1908/EXO1 pathways may enhance our understanding of the patho-mechanisms of osteogenesis in diabetes." (PMID 32454462, 2020).